TBX3 (T-box transcription factor 3)
Diseases named in the same sentence as TBX3 in open-access papers (continued):
Sharing a sentence is not in itself a finding about the gene and the disease.
cancer (continued). "Our finding opened the possibility that the physical interplay between TBX3 and the Wnt pathway might underlie the oncogenic activity that had been associated to its aberrant expression in CRC and other cancers." (PMID 40343989, 2025). "In addition, TBX3 overexpression inhibited GZMB expression on CD8+ T cells, suggesting that TBX3 reduces the cancer-killing efficiency of CD8+ T cells." (PMID 39897553, 2025). "This suggests that the cooperation of TBX3 with Wnt signaling may be a more general feature of Wnt-driven cancers." (PMID 40343989, 2025). "We found that the inhibition of CAFs significantly reduced the cancer-promoting ability of TBX3." (PMID 39897553, 2025). "We found that knockdown of TGFβ1 significantly inhibited the cancer-promoting ability of TBX3." (PMID 39897553, 2025). "However, the most pronounced inhibition of cancer was observed in the group receiving a combination of TBX3 downregulation and anti-PD-1 treatment, indicating a synergistic effect." (PMID 39897553, 2025). "Similarly, the results showed that co-culturing TBX3-overexpressing BLCA cells with CD8+ T cells significantly inhibited the cancer-killing efficiency of the CD8+ T cells." (PMID 39897553, 2025). "Importantly, when TBX2 and TBX3 are depleted in cancers where they are overexpressed, the malignant phenotype is inhibited, and they have therefore been regarded as druggable targets." (PMID 39403898, 2024). "TBX3 can be used as a stem cell marker for many cancer types." (PMID 38965548, 2024). "As cancer advances, TBX3 may further control the aberrant behavior of cell adhesion molecules, synergizing with PDZD2 to contribute to the spread of OS." (PMID 38911382, 2024). "Additionally, the forest plot exhibited the prognostic role of TBX3 in cancers by univariate Cox regression method based on four clinical outcomes." (PMID 38911382, 2024). "Considering the unclear prognostic significance of TBX3 in various cancers, we summarized the correlation between expression of TBX3 with overall survival, disease-specific survival, disease-free interval and progression-free interval based on the univariate Cox regression and Kaplan-Meier models." (PMID 38911382, 2024). "TBX3 behaves as a tumor suppressor or oncoprotein across cancer." (PMID 38909034, 2024). "This study therefore explored targeting TBX2/TBX3 with commercially available non‐cancer drugs." (PMID 39403898, 2024). "There were conflicting reports about the role of TBX3 in different types of cancer." (PMID 38413457, 2024). "By crossing and analyzing different genetic models, we confirm that transcriptional re-activation of TBX3 is an indispensable molecular event for cancer initiation and progression, whereby it links BRAF/MAPK pathway activation to CXCR2 ligands elicited MDSCs infiltration." (PMID 35332119, 2022). "In addition, several of the stem cell switches that we identified, such as Nasp or Tbx3, have been shown to be involved in cancer." (PMID 35037361, 2022). "Furthermore, the overexpression of TBX3 in hMSCs promoted several hallmarks of cancer including stemness, proliferation, migration, and invasion." (PMID 35145908, 2021). "Due to the growing literature implicating TBX3 in the promotion of tumorigenesis in several cancer types, and the observation of tissue- and species-specific TBX3 isoform ratios, it is essential to address the functional relevance of TBX3 isoforms and their altered expression in cancer." (PMID 31570773, 2020). "This suggests that a subset of alternative splicing events may be common across cancer subtypes, which appears to hold true for alternative splicing of TBX3 as well." (PMID 31570773, 2020). "To validate this biologically, we next investigated if depleting TBX3 by shRNA in RD cells could inhibit the cancer phenotype." (PMID 32098189, 2020). "It is well established that TBX3 is aberrantly overexpressed in several cancer types." (PMID 31570773, 2020).
cancer (continued). "Since the 585LFSYPYT591 and 604HRH606 motifs are present in Tbx3 and are involved in liver carcinogenesis, our findings may indicate a novel prognostic indicator and an ideal target for anti-cancer drug development." (PMID 30151243, 2018). "To further explore the putative tumour suppressor activity of TBX3 in fibrosarcomas, we characterized the impact of stably knocking down TBX3 in CT-1 and HT1080 fibroblasts or overexpressing the Tbx3 and Tbx3+2a isoforms in the HT1080 cells on key features of the cancer phenotype." (PMID 26900951, 2016). "Our findings provide novel evidence linking TBX3 to cancers of mesenchymal origin." (PMID 26900951, 2016). "The significance of our findings may have implications for the design of anti-cancer drugs to treat TBX3-driven cancers." (PMID 27110270, 2016). "Together this suggests that the PI3K/AKT pathway may regulate TBX3 via different mechanisms and that this may depend on a developmental versus a cancer context." (PMID 25595898, 2015). "Our finding that TBX3 regulates this process provides fundamental new insights into how altered quantity and molecular function of TBX3 contribute to human developmental disorders and cancer." (PMID 24675841, 2014). "Considering these potential conflicting roles of Tbx3 in breast tumorigenesis, it will be important to further characterize the specific role of Tbx3 in breast tissue before considering inhibition of Tbx3 for cancer therapy." (PMID 25343378, 2014). "The transcription factors TBX2 and TBX3 are overexpressed in various human cancers." (PMID 25344916, 2014). "The splicing function of TBX3 may be a new target for cancer treatment or in tissue regeneration efforts." (PMID 24675841, 2014). "Although Tbx3 exhibits an abnormal expression pattern in various cancers, molecular mechanisms underlying the role of Tbx3 in cancer are not yet entirely revealed." (PMID 23082988, 2012). "In this scenario, over-expression of Tbx3 may render the cancer cells to gain the metastatic capacity and by inhibiting PTEN, may enable cells to resist apoptosis, therefore giving them the chance to survive and migrate to distant sites." (PMID 23082988, 2012). "Over-expression of TBX3 increased the proportion of cancer stem-like cells in MCF7 cells by nine-fold as well as lead to an increase in tumorsphere formation and tumor initiation, suggesting that TBX3 is sufficient to promote normal and cancer stem like cell phenotypes." (PMID 22039763, 2011). "Increasing evidence suggests that Tbx2 and Tbx3 may regulate proliferation in cancer and in development and our data is consistent with a role for these T-box genes downstream of BMP4 in regulating proliferation of the optic cup." (PMID 17173667, 2006). "We then asked whether Tbx3 deletion would impact MASLD-induced cancer." (PMID 40638249, 2025). "Furthermore, there is strong in vitro and in vivo biological evidence that TBX2 and TBX3 are novel targets for the development of anti‐cancer drugs that can be administered on their own or in combination with current chemotherapeutic DNA‐damaging drugs such as cisplatin." (PMID 39403898, 2024). "As for SIRT6, altered TBX3 levels may play different and opposite roles in cancer." (PMID 38081972, 2023). "Similarly, it was shown that estrogen could expand the BCSC pool in multiple human ER+ breast cancer cell lines through activation of a paracrine FGF/FGFR/Tbx3 axis in the cancer cell, greatly increasing tumorsphere formation potential of these cancer cells." (PMID 32391382, 2020). "It is important to note that the results obtained in the soft agar and scratch motility assays were not statistically significant for the cells expressing Flag-Tbx3.These results suggest that Tbx3+2a may be more efficient at promoting these hallmarks of cancer in ERMS." (PMID 32098189, 2020).
cancer (continued). "It would therefore be interesting to determine whether the highly homologous TBX2 and TBX3 have redundant functions in regulating the p21 promoter at this site in cancers where they are both expressed or whether the availability of cofactors may determine which one of the two regulates p21." (PMID 27110270, 2016). "Furthermore, TBX3 activity is increased by WNT signaling in various cancer cell lines." (PMID 25350852, 2014). "Therefore, it is possible that repression of PTEN by Tbx3 may account for resistance to anoikis observed in cancer cells." (PMID 23082988, 2012). "Thus, our data not only reveals a new mechanism that may be important in cancer formation, but also suggests that Tbx3 can be used as a potential biomarker in cancer." (PMID 23082988, 2012). "TBX3, on the other hand, confers tumour drug resistance by bypassing anoikis and promoting the expansion and maintenance of breast and PDAC cancer stem cells." (PMID 40717225, 2025). "In cancer, TGF-β1–induced upregulation of Tbx3 leads to repression of Tbx2, thereby promoting cell migration and invasion." (PMID 41278973, 2025). "First, TBX3 is expressed in cells derived from CRC patients, CRC cell lines, and other Wnt-driven cancers." (PMID 40343989, 2025). "The dysregulated expression of TBX3 affects EMT, tissue integrity, and cell differentiation, thereby controlling the occurrence of malignant tumors." (PMID 36438198, 2022). "Current studies have shown that abnormal expression of TBX3 affects EMT, tissue integrity, and cell differentiation, thereby controlling the occurrence of malignant tumors." (PMID 36438198, 2022). "T-box transcription factor 3 (TBX3) can provoke EMT by positively regulating SNAI1 and SNAI2 in cancer." (PMID 33435156, 2021). "In this study, we show that Tbx3 was dramatically upregulated in clinical HCC samples and that elevated expression of Tbx3 promoted cancer progression." (PMID 30151243, 2018). "These SNPs are located in a cancer-specific enhancer overlapping 9 MCF-7 TAF ChIP-seq data, and are within the TAD containing multiple lincRNAs and TBX3 which is situated 714 kb away." (PMID 24920305, 2014). "Taken together, TBX2 and TBX3 act as suppressors of senescence factors such as CDKNs, and hence, suppress senescence especially in cancer cells; thus, TBX2 and TBX3 are thought to be critical anti-senescence factors." (PMID 22829758, 2012). "We demonstrate that in HNSCC samples, Tbx3 mRNA levels are increased with respect to their normal tissue counterparts (p<0.001), whereas PTEN mRNA levels are significantly reduced in cancer tissues." (PMID 23082988, 2012). "TBX2 and its close relative, TBX3, negatively regulate cell cycle control genes and CDKNs, specifically CDKN2A, CDKN2B, and CDKN1A and are often upregulated in several cancers." (PMID 22829758, 2012). "In this paper we report that in HNSCC samples both the mRNA and protein levels of Tbx3 are increased with respect to their normal tissue counterparts, whereas PTEN mRNA levels are decreased in cancer tissues as it has been reported before." (PMID 23082988, 2012). "At present, no known function was attributed to TBX3 but is frequently overexpressed in a wide range of epithelial and mesenchymal-derived cancers." (PMID 39358558, 2024). "Our study showed that PP reduced the levels of Sox2, c‐Myc and TBX3, suggesting that it may inhibit the clonogenic potential of PDAC cells by targeting these cancer stemness markers." (PMID 39632282, 2024). "TBX3 has no known function in adult tissues but is frequently overexpressed in a wide range of epithelial and mesenchymal-derived cancers." (PMID 35637532, 2022). "In the present study, we found that CAFs secreted TGFβ could increase TROY expression of cancer cells and activate the TROY-mediated PI3K/AKT/TBX3 signaling pathway, promoting stemness properties of HCCs." (PMID 35610614, 2022).
cancer (continued). "Taken together, our data suggest that TBX3 is a powerful oncoprotein in ERMS and that it may be a novel target for therapeutic interventions to treat this cancer." (PMID 32098189, 2020). "The T-box transcription factor 3 (TBX3) is important for lineage decision and cell fate guidance during embryonic development, and the CGI overlapping its promoter and first exon is frequently differentially methylated in cancer." (PMID 24603652, 2014). "In order to determine whether the increase in Tbx3 mRNA level correlates with protein level in HNSCC tissue samples, paraffin embedded cancer and normal tissue sections were stained with anti-Tbx3 antibody." (PMID 23082988, 2012). "Neither the clinical stage nor the origin of cancer exhibited a statistically significant difference in Tbx3 mRNA levels." (PMID 23082988, 2012). "We found TBX3 was significantly negatively correlated with the majority of these steps both in the TCGA-BLCA and Xiangya cohorts, indicating that TBX3 might induce an immunosuppressive microenvironment in BLCA through inhibiting the cancer-immunity cycle." (PMID 39897553, 2025). "It is likely that TBX2 and/or TBX3 account for the function of HDACs in repression of cyclin-dependent kinase inhibitor gene expression in at least some cancer types, and that TBX2 or of its specific interaction with HDACs represent valuable highly specific targets for anti-cancer therapy." (PMID 33731112, 2021). "However, other publications describe an effect of TBX3 overexpression results in a pool of estrogen receptor negative cancer stem-like cells." (PMID 26920143, 2016). "Thus, we hypothesize that Tbx3 may be over expressed in HNSCC and may repress PTEN, thus leading to cancer formation and/or progression." (PMID 23082988, 2012). "However, in our study group neither the clinical stage nor the origin of cancer exhibited a correlation with the Tbx3 mRNA levels." (PMID 23082988, 2012). "Because our aim of this study was to elucidate the implication of aging on carcinogenesis, we then assessed the correlation of age with TBX3 and DKK3 expression in patients without cancer." (PMID 36923312, 2022). "While no studies have previously been published in other cancer cell lines for transient overexpression of TBX4 and 5, numerous studies have shown that transient overexpression of TBX2 or TBX3 does specifically affect senescence by targeting the tumor suppressor gene CDKN1A and B, and CDKN2A." (PMID 30425966, 2018). "However, regulation by Tbx3 has not been demonstrated before for PI3K/PTEN/AKT signalling pathway, which plays very important roles in cancer formation, development and cancer cell metabolism." (PMID 23082988, 2012).
tumor (71 papers, 2006 to 2026). "TBX3 belongs to the T-box transcription factors family, associated with tumor progression and metastasis." (PMID 39290709, 2024). "For patients with metastatic ILC, mutations in CDH1, NF1, PIK3CA, and TBX3, measured as tumor mutational burden (TMB), are higher than for patients with metastatic IDC." (PMID 37428725, 2023). "Motivated by the restricted cell proliferation in mPTC/Tbx3−/− tumor and reduced CXCR2 ligands in TBX3 deficient cells, we investigated the influence of these chemokines on cell proliferation." (PMID 35332119, 2022). "TBX3 is a T-Box TF that has been linked to tumorigenesis by impacting senescence and apoptosis as well as promoting proliferation and tumor formation." (PMID 31910858, 2020). "It is worth noting that TBX2 and TBX3 have been implicated in conferring tumour drug resistance, and because PO can target them, it may be associated with reduced tumour drug resistance." (PMID 40717225, 2025). "To test whether TBX3 acts as a tumor-suppressor in human patients, we looked for putative oncogenic mutations of TBX3 in cBioPortal." (PMID 38081972, 2023). "Failed activation of Tbx3 by genetic ablation dramatically prevents the tumor initiation and ameliorates BRAFV600E-associated reduction of lineage factors, indicating that re-opening of a primitive developmental factor could be a fundamental event for local tumorigenesis." (PMID 35332119, 2022). "Our novel in vivo findings relating to differential tumor-promoting effects between TBX3 isoforms and downstream confirmation of associated pathways suggests that the assessment of relative levels of splice variants may be more important than the assessment of total transcript levels per gene." (PMID 31570773, 2020). "It will be informative to determine which Jak-STAT, TLR, and TGFβ pathway members are direct CAPERα/TBX3 targets, as the complex roles of these pathways in the senescence associated secretory phenotype, inducing or enforcing autocrine and paracrine senescence, and tumor progression are emerging." (PMID 24876127, 2014). "Tumors with low TBX3 expression exhibited inflammatory phenotypes, with a large number of CD8+ T cells infiltrating the tumor area, while tumor-associated fibroblasts infiltrated significantly less." (PMID 39897553, 2025). "We collected tumor tissues for scRNA-seq, which revealed that TBX3 overexpression decreased the percentage of T cells while increasing CAFs." (PMID 39897553, 2025). "Neurocrestal identity factors, such as TBX3, enhance transcriptional plasticity, increasing tumor formation and invasiveness." (PMID 41465101, 2025). "For further spatial analysis, we performed counts of CD8+ T cells and CAFs within the TBX3 expression gradients in tumor cells (CK19+) (0-25 μm, 25-50 μm, 50-100 μm, and 100-150 μm)." (PMID 39897553, 2025). "Single cell RNA sequencing (scRNAseq) of human CRC confirmed TBX3 expression in tumor cell populations corresponding to a considerable 26.4% of all tumor cells." (PMID 40343989, 2025). "Across tumor cell populations, TBX3 expression significantly overlapped with that of BCL9 and BCL9L in individual cells." (PMID 40343989, 2025). "TBX3 overexpression significantly promoted tumor growth in mice, indicating that TBX3 acts as an oncogene in BLCA." (PMID 39897553, 2025). "Secondly, although we established that TBX3 promotes BLCA progression by inducing an immunosuppressive microenvironment, further research is needed to understand why tumor cells highly express TBX3." (PMID 39897553, 2025). "Collectively, these results demonstrated that Usp15 participates in BRAFV600E-induced tumor development by maintaining Tbx3 abundance under genetic background." (PMID 38750011, 2024). "In contrast, in tumor samples with metastasis, the gene group correlated with TBX3 expression was primarily enriched in the cell adhesion molecules pathway." (PMID 38911382, 2024).